TP63 (tumor protein p63)
Diseases named in the same sentence as TP63 in open-access papers (continued):
Sharing a sentence is not in itself a finding about the gene and the disease.
bladder exstrophy (1 paper, 2024). Bladder exstrophy (or classic bladder exstrophy; CEB) is a congenital genitourinary malformation belonging to the spectrum of the exstrophy-epispadias complex (EEC) and is characterized by an evaginated bladder plate, epispadias and an anterior defect of the pelvis, pelvic floor and abdominal wall. "TP63 has been previously reported to be associated with bladder exstrophy and the mouse Tp63 knockout model presents with classic exstrophy of the bladder." (PMID 38903756, 2024).
bladder tumors (1 paper, 2025). "Although the expression of TP63 is maintained in superficial bladder tumors, a loss of TP63 is observed in the more invasive bladder tumors, highlighting that loss of p63 expression promotes cell invasion in bladder cancer." (PMID 39791744, 2025).
blepharitis (1 paper, 2021). Inflammation of the eyelids near the eyelashes. "In our series, tearing secondary to lacrimal disorders including punctal agenesis was the most prevalent symptom, especially in TP63-related disorders (EEC, AEC, RHS), followed by photophobia secondary to dry eye, trichiasis, blepharitis, and corneal disorders." (PMID 33933124, 2021).
carcinoma in situ (1 paper, 2020).
cardiomyopathy (1 paper, 2021). A disease of the heart muscle or myocardium proper. "TP63 might serve as a potential prognostic factor in cardiomyopathy." (PMID 34218797, 2021).
cholesteatoma (1 paper, 2023). A pathologic process characterized by the proliferation of keratinizing squamous epithelium resulting in the accumulation of keratin and cells in the middle ear and/or mastoid.
Clouston syndrome (1 paper, 2022). Clouston syndrome (or hidrotic ectodermal dysplasia) is characterized by the clinical triad of nail dystrophy, alopecia, and palmoplantar hyperkeratosis. "The nail phenotype may be rather specific like in patients with Clouston syndrome or show a wider spectrum of nail plate abnormalities as observed in children with WNT10A or TP63 mutations." (PMID 36421794, 2022).
conjunctival intraepithelial neoplasia (1 paper, 2025). "Elevated TP63 expression has been observed in conjunctival intraepithelial neoplasia (CIN) compared to healthy controls." (PMID 40094891, 2025).
Corneal opacity (1 paper, 2023). A reduction of corneal clarity. "Interestingly, LSCD and corneal opacities are also present in over 60% of patients with TP63 mutation-associated EEC syndrome." (PMID 37856539, 2023).
Cornelia de Lange syndrome (1 paper, 2025). A rare syndrome characterized by low birth weight, delayed growth, intellectual disabillity, behavioral problems, and a distinctive facial appearance (thin, arched eyebrows, low set ears, small teeth, and small nose). "These include the TP63-spectrum of disorders, Apert syndrome, Cornelia de Lange Syndrome (CdLS), and VACTERL/ VATER Association24–27." (PMID 41510282, 2025).
cutaneous squamous cell carcinoma (1 paper, 2020). "Of note, TPRG1 is highly expressed in normal esophageal tissue and an intergenic susceptibility locus (rs6791479) was identified in a genome-wide association study of cutaneous squamous cell carcinoma in between the TP63 and TPRG1 genes." (PMID 32252688, 2020).
developmental delay (1 paper, 2020). "Per the literature, TP63 and CLDN16 genes are related to kidney development and developmental delay." (PMID 32211073, 2020).
diabetes (1 paper, 2021). "Altogether, animal and cell culture data showed a potential role of TP63 as a new candidate gene involved in regulating IRS-1 that may be used as a new therapeutic target to prevent kidney complications in diabetes." (PMID 33920782, 2021). "The role of tumor protein 63 (TP63) in regulating insulin receptor substrate 1 (IRS-1) and other downstream signal proteins in diabetes has not been characterized." (PMID 33920782, 2021).
esophageal tumors (1 paper, 2023). "We found TP63 overexpression in esophageal tumors compared to normal tissues." (PMID 37444412, 2023).
eyelid ptosis (1 paper, 2021). "A new finding of eyelid ptosis or eyelash ptosis was demonstrated in 11 subjects (37%), mostly associated with TP63 or EDA1 genes variants." (PMID 33933124, 2021). "We report a possible genetic association between lash ptosis and EDA1 gene, and eyelid ptosis and TP63 or EDA1 genes variants." (PMID 33933124, 2021). "Our findings suggest that the rate of ptosis in ED subjects, especially those with TP63 and EDA1 gene variants, is higher than previously demonstrated, and that such genetic associations might exist." (PMID 33933124, 2021).
female infertility (1 paper, 2021). Diminished or absent ability of a female to achieve conception. "Although TP63 was not traditionally considered as a primary predictor in female infertility, later research demonstrated its involvement in regulating oocyte fate and fertility." (PMID 34445673, 2021).
HCMV infection (1 paper, 2015). "Important upstream regulators of genes in these downregulated clusters are β-catenin (Pval = 3.96E-11) and TP63 (Pval = 3.14E-11), in agreement with recent studies showing dysregulation of Wnt/β-catenin signaling pathway during HCMV infection." (PMID 26599541, 2015).
Hyperkeratosis (1 paper, 2021). Hyperkeratosis is a histopathological term defining a thickened stratum corneum and may be present in many different skin conditions, with many possible overlaps. "SATB1 and p63, transcription and remodelling factors encoded by SATB1 and TP63, may contribute to the phenotype of hyperplasia and hyperkeratosis." (PMID 34322157, 2021).
immune deficiency (1 paper, 2024). "It is worth noting that no alternative underlying causes for the observed T-cell lymphopenia were identified in the patient, suggesting that the immune deficiency is most likely associated with the TP63 variant." (PMID 39409174, 2024).
influenza (1 paper, 2021). An acute viral infection of the respiratory tract, occurring in isolated cases, in epidemics, or in pandemics; it is caused by serologically different strains of viruses (influenzaviruses) designated A, B, and C, has a 3-day incubation period, and usually lasts for 3 to 10 days. "Since recellularization of an acellular scaffold differs from influenza triggered structural repair, these findings suggest that the regenerative capabilities of TP63+ basal cells are heterogeneous and injury dependent." (PMID 33674599, 2021).
invasive breast carcinoma (1 paper, 2019). A carcinoma that infiltrates the breast parenchyma. "Overexpression of DCAF13, DNMT3B, KPNA2, EXO1, FANCI, RACGAP1, and ZNF106 in invasive breast carcinoma patients showed poor survival, while overexpression of CDKN2A, SORBS1, and TP63 showed better survival." (PMID 32010179, 2019).
Legius syndrome (1 paper, 2025). Legius syndrome, also known as NF1-like syndrome, is a rare, genetic skin pigmentation disorder characterized by multiple cafC)-au-lait macules with or without axillary or inguinal freckling. "Case 35 with digenic findings SPRED1 p.Arg325Ter and TP63 p.Pro428Leu presented characteristic features of Legius syndrome (linked to SPRED1)." (PMID 40060932, 2025).
leukoplakia (1 paper, 2023). A white patch or plaque on a mucous membrane that cannot be characterized clinically or pathologically as any other disease. "Some epithelial cells in leukoplakia showed CNVs as well as expression of various tumor-related genes similar to malignant cells, suggesting that CNV-driven expression of TP63 and ATP1B3 in leukoplakia plays a critical role in the progression to HNSCC." (PMID 38188682, 2023).
lung disease (1 paper, 2024). "Nevertheless, these results suggest that loss of SOX2 may contribute to Wnt activation and TP63 expression in KRT5−/KRT17+ dysplastic cells of IPF and pathological remodeling in human lung disease." (PMID 38182591, 2024).
medulloblastoma (1 paper, 2020). A malignant, invasive embryonal neoplasm arising from the cerebellum. "We found that among the selected genes, three of the downregulated genes (BOC, VCAM1, and TP63) followed the same pattern as ERBB4 and showed a higher expression in Group 4 medulloblastomas." (PMID 32316671, 2020). "Finally, we correlated their expression with patient outcome finding that altered VCAM1, TP63, ANKRD1, THBS1, and PTHLH levels correlated with lower patient survival in Group 4 medulloblastoma samples." (PMID 32316671, 2020). "Next, we moved our attention to genes already related to medulloblastoma based on the literature and validated some of them, such as POSTN, BOC, VCAM1, and TP63 among the downregulated genes and ANKRD1, THBS1, NRG1, PTHLH, and HBEGF among the upregulated ones in DAOY and D283Med cells." (PMID 32316671, 2020).
metastatic melanoma (1 paper, 2011). A melanoma that has spread from its primary site to another anatomic site. "Subsequent analysis of these datasets confirmed that the expression of TP63 is down regulated in metastatic melanoma." (PMID 21951600, 2011).
multicystic dysplastic kidney (1 paper, 2020). Multicystic dysplastic kidney (MCDK) is a congenital anomaly of the kidney and urinary tract (CAKUT) in which one or both kidneys (unilateral or bilateral MCDK respectively) are large, distended by multiple cysts, and non-functional. "Our case expands the phenotypic spectrum of TP63‐related disorders to include multicystic dysplastic kidneys and anhydramnios as a prenatal lethal presentation of EEC due to the His247Arg pathogenic variant." (PMID 32881366, 2020).
myelodysplastic syndrome (1 paper, 2014). A clonal hematopoietic disorder characterized by dysplasia and ineffective hematopoiesis in one or more of the hematopoietic cell lines.
myeloid neoplasm (1 paper, 2022). Proliferation of myeloid cells originating from a primitive stem cell. "For example, distinct 5hmC levels within TP63 and MYBL2 binding regions were significantly associated with the survival of patients with myeloid neoplasms." (PMID 35765052, 2022).
nail disorder (1 paper, 2022). A disease involving the nail. "TP63 variants were regularly associated with nail disorders." (PMID 36421794, 2022).
nasopharyngeal carcinoma (1 paper, 2024). A carcinoma arising from the nasopharyngeal epithelium. "For instance, ΔNP63α is a prominent isoform of TP63, driven by SEs associated with basal cell-specific genes in nasopharyngeal cancer (NPC) cells." (PMID 38542080, 2024).
non-Hodgkin lymphoma (1 paper, 2016). Distinct from Hodgkin lymphoma both morphologically and biologically, non-Hodgkin lymphoma (NHL) is characterized by the absence of Reed-Sternberg cells, can occur at any age, and usually presents as a localized or generalized lymphadenopathy associated with fever and weight loss. "Accordingly, in tumors structural disruption of TP63 and aberrant p63 expression are commonly seen in squamous cell and transitional cell carcinomas, but are also observed in non-Hodgkin lymphomas, predominantly in diffuse large B-cell lymphoma (DLBCL) and follicular lymphoma (grade 2 and 3)." (PMID 26878872, 2016).
oral squamous cell carcinoma (1 paper, 2017). "This study aimed to explore the role of TP63 in the progression of oral squamous cell carcinoma (OSCC)." (PMID 28423539, 2017).
ovarian insufficiency (1 paper, 2021). "The current clinical literature reporting TP63-related ovarian insufficiency is diverse in patient presentations and includes isolated POI and syndromic POI with RHS, LMS, and AEC." (PMID 34445673, 2021).
polycystic kidney disease (1 paper, 2024). A usually autosomal dominant and less frequently autosomal recessive genetic disorder characterized by the presence of numerous cysts in the kidneys leading to end-stage renal failure. "Three of six fetuses with polycystic kidney disease and extra-renal abnormalities displayed a pathogenic variant (INVS, TP63, CEP290)." (PMID 37535131, 2024).
prostate tumors (1 paper, 2018). "In contrast, expression of basal markers (TP63, KRT5) was significantly increased in the ‘low’ NKX3.1 prostate tumors." (PMID 30266798, 2018).
scleroderma (1 paper, 2022). Scleroderma is a rare autoimmune connective tissue disorder characterized by abnormal hardening of the skin and, sometimes, other organs. "In contrast to the untreated scleroderma mice group, the ability of endothelial development associated proteins (LAMC2, PLOD3, and TP63) recovered in the treatment group." (PMID 35315234, 2022). "Immunofluorescence stainings revealed that the expression levels of epidermal stem cell markers (KRT14 and TP63) and mature epidermal marker (KRT10) were downregulated in scleroderma, while these proteins were recovered to normal levels in the treatment group." (PMID 35315234, 2022).
small cell carcinoma (1 paper, 2022). A neuroendocrine carcinoma composed of small malignant cells which are often said to resemble "oat cells" under the microscope. "TP63 and TTF-1 are useful for distinguishing both small cell carcinomas as well as AC from SCC." (PMID 35584089, 2022).
T-cell large granular lymphocyte leukemia (1 paper, 2022). T-cell large granular lymphocyte leukemia (T-cell LGL leukemia) is a lymphoproliferative malignancy that arises from the mature T-cell (CD3+) lineage. "Interestingly, T-cell large granular lymphocyte leukemia (T-LGL) cell line MOTN-1 also showed elevated TP63 levels." (PMID 36009586, 2022).
thymic carcinoma (1 paper, 2023). Thymic carcinoma (TC) is a type of thymic epithelial neoplasm characterized by a high malignant potential. "In an effort to understand why markers of tuft cells and ionocytes are preferentially expressed in thymic carcinomas, we investigated the distribution of the common squamous cell markers, KRT5 and TP63, in the adult thymus." (PMID 38201543, 2023).
thymoma (1 paper, 2017). A neoplasm arising from the epithelial cells of the thymus. "Thus TP63/TP73 may be promising new targets for treating thymomas." (PMID 28258440, 2017). "Additionally, overexpression of TP63 and TP73 was frequently observed in thymomas." (PMID 28258440, 2017).
tumor (234 papers, 2001 to 2026). "To further elucidate the molecular basis underlying decursin’s anti-tumor effects, we examined two malignancy-associated proteins (TP63 and SOX-2) under varying treatment durations (0 h, 24 h, 48 h, and 72 h) and concentrations (0 μM, 10 μM, 20 μM, and 40 μM)." (PMID 40508204, 2025). "In line with the tumor-intrinsic role of TP63, loss of TP63 (shTrp63 + IgG2a) decreased the tumor volume compared with the control (Scrmable + IgG2a) group." (PMID 38509096, 2024). "While TP63 can function as a tumor suppressor, its overexpression or mutations can also be associated with certain cancers." (PMID 39409174, 2024). "CircRNA TP63 (circTP63) has been implicated in cell proliferation and invasion in some tumor progress." (PMID 34789260, 2021). "With the exception of tumor 2, all tumor samples showed characteristic mutations of HNSCC including amplification of 3q26.2 (TP63, SOX2, PIK3CA), 5q14.3 (APC), 8q24.3 (PTK2), 8q22.3 (LRP12) as well as loss and/or LOH of 9p21.3 (CDKN2A)." (PMID 32426287, 2020). "Tumour regression upon TP63 excision is associated with decrease of expression of ECM‐related proteins, such as collagen COL6A2 and COL17A1, LAMB3 and ITGB4." (PMID 30845357, 2019). "A study of 103 OSCC patients revealed that TP63 expression level was closely associated with tumor progression." (PMID 28423539, 2017). "Previous studies have shown that, whereas the truncated ΔNP63 isoform can promote tumor growth, loss of the full-length TP63 expression enhances invasion and migration of cancer cells as well as their ability to metastasize to distal organs." (PMID 26208975, 2015). "In addition, antibody depletion of CD8+ T cells significantly reversed the reduction of tumor volume caused by shTP63 and PD-1 mAb treatment, demonstrating that the function of TP63 in immune response is mediated through CD8+ T cells." (PMID 38509096, 2024). "These independent observations from patient samples underscore the importance of TP63 in regulating anti-tumor immune response, and suggest that TP63 expression might serve as a biomarker associated with immune-cold tumors in SCCs." (PMID 38509096, 2024). "We identified some mutation markers specific to tumor types, including some typical tumor‐related genes (e.g., TP63, ABCC1, ABCC5, and TFDP1 in ESCA) as well as numerous noncoding genes (e.g., NPSR1‐AS1 and AC079466.1 in HCC) and pseudogenes (e.g., SDHAP3 and TPTEP1 in LUAD)." (PMID 38010945, 2024).